CBX7 (chromobox 7)
Description:
Component of a Polycomb group (PcG) multiprotein PRC1-like complex, a complex class required to maintain the transcriptionally repressive state of many genes, including Hox genes, throughout development. PcG PRC1 complex acts via chromatin remodeling and modification of histones; it mediates monoubiquitination of histone H2A 'Lys-119', rendering chromatin heritably changed in its expressibility. Promotes histone H3 trimethylation at 'Lys-9' (H3K9me3). Binds to trimethylated lysine residues in histones, and possibly also other proteins. Regulator of cellular lifespan by maintaining the repression of CDKN2A, but not by inducing telomerase activity.
Tractability: Small molecule: a high-quality ligand is known; it has a binding pocket of medium quality. PROTAC: its protein half-life has been measured; a small molecule that binds it is known.
Target class: Epigenetic regulator; Reader; Methyl-lysine/arginine binding protein; Chromodomain
Chemical probes: UNC3866
Gene: Protein-coding gene on chromosome 22 (39,120,167 to 39,152,719, reverse strand). Ensembl gene ENSG00000100307.
Subcellular location: Nucleus
Subcellular location (Human Protein Atlas): Nucleoplasm; Cytosol
Gene Ontology:
Molecular function: protein binding
Biological process: negative regulation of transcription by RNA polymerase II; heterochromatin formation; negative regulation of DNA-templated transcription
Cellular component: chromatin; cytosol; nucleoplasm; nucleus; PcG protein complex; PRC1 complex
Genetic constraint (gnomAD): Loss-of-function variants: 13 observed, 26.96 expected, observed/expected ratio (o/e) 0.48, 90% interval 0.31 to 0.77. The upper end of that interval is the gene's LOEUF score, 0.77, which puts it in group 3 of 6, group 1 being the genes least tolerant of losing a copy. Missense variants: 259 observed, 296.01 expected, observed/expected ratio (o/e) 0.87, 90% interval 0.79 to 0.97. Synonymous variants: 149 observed, 132.7 expected, observed/expected ratio (o/e) 1.12, 90% interval 0.98 to 1.29.
Homologues: Orthologues: pig CBX7 (96% identical), chimpanzee CBX7 (94% identical), macaque CBX7 (94% identical), rat Cbx7 (90% identical), mouse Cbx7 (88% identical), rabbit CBX7 (88% identical), guinea pig CBX7 (80% identical), dog CBX7 (70% identical), tropical clawed frog cbx7 (61% identical), zebrafish cbx7b (43% identical), zebrafish cbx7a (41% identical), Caenorhabditis elegans set-31 (18% identical), and 1 more. Paralogues in human: CBX6 (35% identical), CBX8 (34% identical), CBX2 (32% identical), CBX4 (31% identical), CBX1 (18% identical), CBX3 (17% identical), CBX5 (15% identical), NPTXR (12% identical).
Diseases named in the same sentence as CBX7 in open-access papers:
CBX7 is named in the same sentence as 80 diseases in open-access papers, as found by Europe PMC text mining. Sharing a sentence is not in itself a finding about the gene and the disease. The quoted sentences say what the papers report.
prostate carcinoma (25 papers, 2013 to 2025). A carcinoma that arises from epithelial cells of the prostate gland. "As we hypothesized that miR-375 mediated prostate cancer progression might be explained by its targeting of CBX7, we examined the associations between CBX7 expression in prostate cancer tissue samples and tumor status and Gleason Scores (GSE29079)." (PMID 27449098, 2016). "Furthermore, CBX7 absence was also associated with lymph node metastases and prostate cancer specific death." (PMID 27449098, 2016). "To investigate whether CBX7 loss leads to upregulation of CBX8 in prostate cancer cells, we transfected LNCaP cells with siRNAs against CBX7, thereby emulating the effect of miR-375 de-repression." (PMID 27449098, 2016). "Tissue analysis showed association of CBX7 loss with advanced prostate cancer." (PMID 27449098, 2016). "Moreover, we observed CBX7 loss in lymph node metastases and showed that this correlates with prostate cancer specific death." (PMID 27449098, 2016). "Then we further clarified the expression of CBX family members in prostate cancer, which result showed that CBX5, CBX6 and CBX7 were significantly down-regulated in prostate cancer tissues, while CBX3, CBX2, CBX4 and CBX8 was notably up-regulated." (PMID 40861818, 2025). "Meanwhile, several studies also demonstrated an oncogenic role of CBX7 in multiple types of human cancers, including prostate cancer, lymphoma, and gastric cancer." (PMID 37791390, 2024). "On the contrary, some studies have revealed that CBX7 was overexpressed in prostate cancer, GC and lymphoma." (PMID 36140750, 2022). "In contrast, in prostate cancer and ovarian cancer, CBX7 is upregulated and acts as a tumor promoter." (PMID 34395271, 2021). "Generally, androgens are favorable factors for prostatic cancer development, but CBX7 plays an important role in maintaining prostate cancer cells growth by cooperating with C-MYC with androgen-independent transformation." (PMID 34659360, 2021). "Small molecules such as suramin and Ms37452 can inhibit the binding of lysine methylated polypeptides to the CBX7 chromodomain, which can be used as a feasible cancer suppressor in some cancers with high CBX7 expression, such as prostate cancer." (PMID 34659360, 2021). "Recently, it has been reported that GOLPH3 can bind to the CBX7 protein in prostatic cancer to promote cell proliferation and inhibit cell apoptosis." (PMID 34659360, 2021). "There are exceptions, however; CBX7 acts as an oncogene in lymphoma and prostate cancer, and CBX6 acts as an oncogene in hepatocellular carcinoma." (PMID 34617019, 2021). "LncRNA ANRIL is upregulated in prostate cancer, interacting with the chromobox 7 (CBX7) protein, part of the polycomb group protein regulator of cytokinesis (PRC1) protein complex." (PMID 32489713, 2020). "For instance, CBX7 governs the growth of prostate cancer cells via repression of the Ink4a/Arf locus." (PMID 31709304, 2019). "The lncRNA ANRIL has been shown to be upregulated and repress INK4b-ARF-INK4a locus epigenetically by recruiting CBX7 in prostate cancer." (PMID 30038703, 2018). "High expression of CBX7 was observed in tumors of blood system and prostate cancer, suggesting an oncogenic role." (PMID 29422082, 2018). "While the INK4b/ARF/INK4a locus is shown to undergo deletion in GBM, epigenetic transcriptional repression of the locus by a repressive complex containing ANRIL and CBX7 has also been shown in prostate cancer." (PMID 30038703, 2018). "On the other hand, over-expression of CBX7 had also been found in some malignancies, such as prostate cancers and ovarian cancers." (PMID 30481161, 2018). "CBX7 was upregulated in prostate cancer and gastric cancer while declined in thyroid cancer, lung cancer and colon cancer." (PMID 29190923, 2017).
prostate carcinoma (continued). "Our study indicates that miR-375 exerts its tumor-promoting role in prostate cancer by influencing the epigenetic regulation of transcriptional programs through its ability to directly target the Polycomb complex member CBX7." (PMID 27449098, 2016). "CBX7 absence in lymph node metastases was independent from the CBX7 status of the primary prostate cancer samples of the same patients (p = 0.530, Pearson Chi2 test, two-sided)." (PMID 27449098, 2016). "To investigate the molecular signatures induced by CBX7 repression in prostate cancer cells, we performed expression profiling following siCBX7 knockdown and integrated our data with known CBX7 targets." (PMID 27449098, 2016). "In parallel, we investigated CBX7 expression in lymph node metastases from 58 prostate cancer patients by tissue microarray." (PMID 27449098, 2016). "We next analyzed the molecular signatures following CBX7 silencing in prostate cancer cells after 48 h using global microarray analysis." (PMID 27449098, 2016). "MiR-375-mediated repression of CBX7 was accompanied by increased expression of its homolog CBX8 and activated transcriptional programs linked to malignant progression in prostate cancer cells." (PMID 27449098, 2016). "While some studies showed that Cbx7 behaved as an oncogene in lymphoma, prostate cancer, ovarian cancer, and gastric cancer, other studies indicated Cbx7 was acting as a tumor suppressor gene in the bladder, colon, pancreas, and thyroid cancers." (PMID 25881303, 2015). "Accordingly, in the prostate cancer cell line PC-3 ANRIL was found to interact with CBX7 and the expression of p16INK4A was diminished." (PMID 29861427, 2015). "Interestingly, CBX7 was previously reported to synergize with c-MYC to promote the growth of prostatic cancer cells or cooperate with c-MYC to produce highly aggressive B cell lymphomas, acting as an oncogene and positively correlating with c-MYC." (PMID 37791390, 2024). "Moreover, in prostate cancer, circCSNK1G3 promotes cell growth by interacting with miR-181 involved in the regulation of CBX7." (PMID 34659360, 2021). "CBX7 promotes proliferation of prostate cancer cells and malignant hematopoietic progenitor cells." (PMID 34617019, 2021). "However, studies on the relationship between circRNA and CBX7 are few and currently limited to prostate cancer." (PMID 34659360, 2021). "In prostate cancer, CBX7 is also positively correlated to cancer progression." (PMID 34659360, 2021). "However, high expression levels of CBX7 were associated with a reduced OS and DFS in patient with prostate cancers and ovarian cancers." (PMID 34046352, 2021). "In addition, miR-375 plays a cancer-promoting role in prostate cancer by influencing the epigenetic regulation of transcriptional programs through its ability to directly target the polycomb complex member CBX7." (PMID 34659360, 2021). "For instance, CBX7 is upregulated in follicular lymphoma and prostate cancer." (PMID 31211140, 2019). "Interestingly, CBX7 seems to positively regulate miR-323: this can account for the reduced miR-323 expression in prostate cancer where CBX7 is drastically downregulated and miR-323 has a tumor suppressor activity by targeting AdipoRI." (PMID 28259135, 2017). "In addition, CBX7 activity has been reported to be negatively correlated to malignancy grade in breast, thyroid, pancreatic cancer, prostate cancer, bladder cancer, lung cancer and colon cancer." (PMID 28388562, 2017). "MiR-375-mediated repression of CBX7 leads to higher levels of CBX8 in prostate cancer cells." (PMID 27449098, 2016). "In mammals, MEL18 and CBX7 have also been proposed to act as a tumor suppressor in prostate cancer." (PMID 24358021, 2013).
prostate carcinoma (continued). "Interestingly, CBX7 was initially identified as an oncogene in prostate cancer, lymphoma, and gastric cancer due to its inhibitory effect on INK4a/ARF locus, while several other studies reported the tumor suppressor roles of CBX7 in ovarian, thyroid, lung, pancreatic, and colon tumors." (PMID 37791390, 2024). "Two well-characterized small compound CBX7 inhibitors, MS351 and MS37452, have previously been tested in the treatment of prostate cancer." (PMID 39402138, 2024). "Multiple pharmacological compounds targeting the PcG proteins are under development and are studied in cancer biology, of which the CBX7-inhibitor MS452 has been demonstrated to block binding of CBX7 to the INK4A/ARF locus and thereby derepress cell cycle arrest genes in prostate cancer." (PMID 40552137, 2024). "Moreover, in prostate cancer, C-C motif chemokine ligand 2 (CCL2) is a main target of PRC1, and the H3K27me3 inhibitory marker that is bound with CBX7 is relatively low in the promoter region of the CCL2 gene, which leads to massive production of CCL2." (PMID 34659360, 2021). "In several studies on prostatic cancer, CBX family members, including CBX7, were shown to facilitate PRC1-mediated transcriptional repression by targeting the complex to tri-methylated lysine 27 of histone H3, inducing chromatin compaction, DNA methylation and repression of the underlying genes." (PMID 28388562, 2017). "Interestingly, the INK4/ARF locus encodes such a regulatory lncRNA named ANRIL, which has been shown to interact with the PcG proteins CBX7 in the prostate cancer cell line PC-3 and SUZ12 in normal lung fibroblasts, respectively." (PMID 29861427, 2015).
gastric cancer (23 papers, 2010 to 2025). A primary or metastatic malignant neoplasm involving the stomach. "Recent reports have indicated that higher mRNA expression of CBX3-6 and lower mRNA expression of CBX7 were significantly associated with poor prognosis and survival rate of gastric cancer patients." (PMID 35464847, 2022). "This study was to investigate the role of CBX7 in regulating stem cell-like properties of gastric cancer and the underlying mechanisms." (PMID 29422082, 2018). "CBX7 was downregulated in gastric cancer tissues compared to normal tissues, and this downregulation of CBX7 was closely related to poor OS." (PMID 35464847, 2022). "Expression levels of CBX1/2/3/4/8 in gastric cancer samples were significantly upregulated, whereas mRNA expressions of CBX7 were significantly downregulated compared to the normal control in unpaired and paired analysis." (PMID 35969177, 2022). "CBX7 was thought to be related to the proliferation and metastasis of the gastric cancer cell and be able to reveal the prognosis." (PMID 36339684, 2022). "CBX7 expression was significantly down-regulated in tumor samples, consistent with outcomes in other gastric cancer types." (PMID 35969177, 2022). "CBX7 positively regulates the phenotype of gastric cancer stem cells by downregulating p16 and upregulating microRNA-21." (PMID 35969177, 2022). "In gastric cancer, CBX7 actively regulates the stem cell characteristics of gastric cancer cells through the AKT-NF-kB-miR-21 pathway." (PMID 34659360, 2021). "In recent years, studies have found that CBX7 was a component of polycomb repressive complex 1, maintaining the stem cell–like characteristics of gastric cancer cells by activating the AKT pathway and down-regulating p16." (PMID 33747044, 2021). "The transcription levels of CBX2, CBX3, CBX4 and CBX5 were significantly enhanced, whereas the mRNA level of CBX7 was decreased in gastric cancer tissues compared with normal tissues." (PMID 34117289, 2021). "One group reports that miR-421 decreases cell growth via upregulation of CBX7 in gastric cancer cells." (PMID 31709304, 2019). "Downregulation of CBX7 inhibited cellular proliferation and migration ability via increased p16 in gastric cancer." (PMID 31709304, 2019). "For example, higher expression of CBX7 was correlated with clinical stage and lymph node metastasis in gastric cancer." (PMID 31709304, 2019). "Collectively, these results suggest that CBX7 regulate stem cell-like characteristics of gastric cancer cells via AKT-NF-κB pathway and miR-21." (PMID 29422082, 2018). "Our data suggested that CBX7 was significantly overexpressed in the oncospheres of p16-deleted MKN28 gastric cancer cells, and CBX7 overexpression resulted in the upregulation of GCSC phenotype such as sphere formation." (PMID 29422082, 2018). "Next, we investigated the potential mechanisms by which CBX7 regulates stem cell-like characteristics of gastric cancer cells." (PMID 29422082, 2018). "Firstly, the role of CBX7 in regulating stem cell-like properties of gastric cancer was investigated using sphere formation, Western blot, and xenograft tumor assays." (PMID 29422082, 2018). "The expression of CBX7, its downstream targets, and stem cell markers were analyzed in gastric stem cell spheres, common cancer cells, and gastric cancer tissues." (PMID 29422082, 2018). "Restoring the expression of p16 partially abrogated CBX7-triggered stem cell properties of gastric cancer cells." (PMID 29422082, 2018). "We overexpressed constitutively active form of AKT (pSRα-mAkt) in CBX7-depleted gastric cancer cells and determined its effect on oncogenic characteristics, including GCSC phenotypes." (PMID 29422082, 2018). "Collectively, these data suggest that CBX7 positively regulates gastric cancer stem cell (GCSC) phenotype." (PMID 29422082, 2018). "CBX7 positively regulates stem cell-like characteristics of gastric cancer cells by inhibiting p16 and activating AKT-NF-κB-miR-21 pathway." (PMID 29422082, 2018).